MIR520F (microRNA 520f)
Synonyms: hsa-mir-520f; MIRN520F; mir-520f
Gene: MicroRNA gene on chromosome 19 (53,682,159 to 53,682,245, forward strand). Ensembl gene ENSG00000283540.
Gene Ontology:
Biological process: miRNA-mediated post-transcriptional gene silencing
Homologues: Orthologues: chimpanzee ptr-mir-520f (100% identical). Paralogues in human: MIR520C (90% identical), MIR516A1 (89% identical), MIR519A2 (89% identical), MIR519C (89% identical), MIR516A2 (87% identical), MIR523 (87% identical), MIR522 (86% identical), MIR516B1 (85% identical), MIR518E (85% identical), MIR519B (84% identical), MIR520E (84% identical), MIR521-1 (84% identical), and 12 more.